SNORD125 (small nucleolar RNA, C/D box 125)
Gene: Small nucleolar RNA gene on chromosome 22 (29,333,163 to 29,333,258, reverse strand). Ensembl gene ENSG00000239127.
Gene Ontology:
Biological process: RNA processing
Cellular component: nucleolus
Homologues: Orthologues: chimpanzee SNORD125 (100% identical), macaque SNORD125 (100% identical), rabbit SNORD125 (88% identical), pig SNORD125 (86% identical), rat Snord125 (85% identical), guinea pig SNORD125 (84% identical), mouse Gm24958 (81% identical).